NLRP10 (NLR family pyrin domain containing 10)
Description:
Inhibits autoprocessing of CASP1, CASP1-dependent IL1B secretion, PYCARD aggregation and PYCARD-mediated apoptosis but not apoptosis induced by FAS or BID. Displays anti-inflammatory activity. Required for immunity against C.albicans infection (By similarity). Involved in the innate immune response by contributing to pro-inflammatory cytokine release in response to invasive bacterial infection. Contributes to T-cell-mediated inflammatory responses in the skin (By similarity). Plays a role in protection against periodontitis through its involvement in induction of IL1A via ERK activation in oral epithelial cells infected with periodontal pathogens. Exhibits both ATPase and GTPase activities.
Synonyms: NALP10; NOD8; PYNOD; PAN5; CLR11.1
Tractability: Antibody: UniProt places it where antibodies can reach, with high confidence; its Gene Ontology location is reachable by antibodies, with medium confidence.
Gene: Protein-coding gene on chromosome 11 (7,957,537 to 7,965,447, reverse strand). Ensembl gene ENSG00000182261.
Subcellular location: Cytoplasm; Cell membrane
Subcellular location (Human Protein Atlas): Nucleoplasm; Cytosol
Gene Ontology:
Molecular function: ATP hydrolysis activity; GTPase activity
Biological process: activation of innate immune response; positive regulation of defense response to bacterium; positive regulation of interleukin-1 alpha production; positive regulation of interleukin-6 production; positive regulation of interleukin-8 production; defense response to fungus; positive regulation of inflammatory response; positive regulation of T-helper 1 type immune response; positive regulation of T-helper 17 type immune response; regulation of inflammatory response; positive regulation of defense response; positive regulation of immune response
Cellular component: cytoplasm; cytoplasmic side of plasma membrane; cytosol; plasma membrane
Genetic constraint (gnomAD): Loss-of-function variants: 5 observed, 8.33 expected, observed/expected ratio (o/e) 0.6, 90% interval 0.31 to 1.26. That is too few expected variants to judge how well the gene tolerates losing a copy. Missense variants: 808 observed, 809.23 expected, observed/expected ratio (o/e) 1, 90% interval 0.94 to 1.06. Synonymous variants: 337 observed, 328.7 expected, observed/expected ratio (o/e) 1.03, 90% interval 0.94 to 1.12.
Homologues: Orthologues: chimpanzee NLRP10 (99% identical), macaque NLRP10 (95% identical), rabbit NLRP10 (71% identical), dog NLRP10 (70% identical), rat Nlrp10 (60% identical), mouse Nlrp10 (59% identical), zebrafish nlrp1 (21% identical), zebrafish nlrb5 (20% identical), zebrafish si:ch211-66k16.2 (17% identical). Paralogues in human: NLRP3 (30% identical), NLRP12 (29% identical), NLRP1 (24% identical), NLRP9 (23% identical), NLRP6 (22% identical), NLRP4 (21% identical), NLRP14 (21% identical), NLRP2 (21% identical), NLRP7 (21% identical), NLRP5 (19% identical), NLRP8 (18% identical), NOD2 (17% identical), and 8 more.
Diseases named in the same sentence as NLRP10 in open-access papers:
NLRP10 is named in the same sentence as 24 diseases in open-access papers, as found by Europe PMC text mining. Sharing a sentence is not in itself a finding about the gene and the disease. The quoted sentences say what the papers report.
atopic dermatitis (6 papers, 2013 to 2025). "However, GWAS have linked NLRP10 to atopic dermatitis, an interesting find considering the abundant expression of NLRP10 in the skin." (PMID 24137163, 2013). "This interaction may enhance NOD1 signaling through NLR family pyrin domain containing 10 (NLRP10) expression in epidermal and dermal fibroblast-like cells, potentially influencing innate immune responses and exhibiting the associations with atopic dermatitis and allergic contact dermatitis." (PMID 41227429, 2025). "Our findings underscore NLRP10 as a key player in atopic dermatitis pathogenesis, highlighting NLRP10 as a potential target for therapeutic intervention to restore skin barrier function and homeostasis in AD." (PMID 39424623, 2024). "Whether genetic variants in NLRP10 predispose humans to inflammatory bowel disease is not known, but genetic variants of NLRP10 have been linked to an increased risk of developing the inflammatory skin disease atopic dermatitis." (PMID 39351983, 2025).
cutaneous leishmaniasis (2 papers, 2019 to 2023). Leishmaniasis affecting the skin. "For instance, in mouse models of contact hypersensitivity and cutaneous leishmaniasis it was shown that NLRP10 can both promote proinflammatory or anti-inflammatory immune responses, dependent on the context." (PMID 37325658, 2023). "Other models of cutaneous leishmaniasis, including studies of gene knockout mice (NLRP10 and TNFRp55) describe enhanced lesion severity without an associated increase in L. major burden." (PMID 31107882, 2019).
inflammatory skin disease (2 papers, 2024 to 2025). Inflammatory skin disorders covers a broad category that includes many conditions ranging in severity, from mild itching to grave medical health complications These disorders are common in people of all ages and races. "In summary, our data characterize an important role of NLRP10 in promoting keratinocyte survival and epidermal barrier function, which are frequently altered in inflammatory skin diseases such as AD." (PMID 39424623, 2024).
intestinal inflammation (2 papers, 2025). "Given that NLRP10 deficiency promotes skin inflammation in humans and exacerbates intestinal inflammation in mice, therapeutic strategies aimed at restoring or enhancing NLRP10 function may represent promising anti-inflammatory approaches." (PMID 41062723, 2025). "Given that loss‐of‐function in NLRP10 promotes skin inflammation in humans and that mice lacking NLRP10 develop intestinal inflammation, strategies aimed at activating NLRP10 could lead to new anti‐inflammatory therapies." (PMID 39351983, 2025).
ischemic stroke (2 papers, 2020). A stroke disorder caused by obstruction of blood flow to the brain, due to thrombotic (local blood clot formation) or embolic (due to a blood clot or other material traveling from another site) event. "Recent studies showed that various inflammasomes, containing NLRP1, NLRP2, NLRP3, NLRP10, NLR family card domain containing 4 (NLRC4), and absent in melanoma 2(AIM2) 35-39, are activated in ischemic stroke." (PMID 32788872, 2020).
Candida infection (1 paper, 2013). "In line with this, NLRP10-deficient mice have increased susceptibility to disseminated Candidiasis, as indicated by decreased survival and increased fungal burdens, secondary to impaired induction of Candida-specific Th1 and Th17 responses." (PMID 24409181, 2013). "It still remains to be determined how NLRP10 activity is triggered during Candida infection and the molecular function of NLRP10 that regulates DC migration." (PMID 24409181, 2013).
colitis (1 paper, 2016). Inflammation of the colon. "Although deficiency in other inflammasome components, including ASC, caspase-1, and IL-18, also led to dysbiosis and exacerbated colitis, deficiency in NLRC4, NLRP10, NLRP12, and AIM2 had no impact on the susceptibility of WT mice to colitis upon cohousing." (PMID 26925061, 2016).
endometrial cancer (1 paper, 2025). Primary or metastatic malignant neoplasm involving the endometrium (mucous membrane that lines the endometrial cavity). "Moreover, NLRP10 is associated with a poor prognosis in endometrial cancer by inhibiting NF-κB activation and apoptosis, along with caspase-1-mediated IL-1β maturation." (PMID 40124684, 2025).
melanoma (1 paper, 2024). A malignant, usually aggressive tumor composed of atypical, neoplastic melanocytes. "To confirm and extend this finding in human disease, we observed that NLRC4 expression (but not NLRP10 used as control) strongly correlated with expression of the type I IFN genes induced in the NLRC4-expressing cell lines in various patient cancer samples (colon, lung, and melanoma)." (PMID 38652550, 2024).
prostate tumours (1 paper, 2015). "Several other genes at this locus, including CYB5R2, EIF3F, NLRP10, OLFML1 and OVCH2, were also found to be significantly expressed in prostate tumours in comparison with normal tissues." (PMID 26443449, 2015).
skin cutaneous melanoma (1 paper, 2024). "Importantly, consistent with our finding showing a role for NLRC4 in protecting against metastatic progression in CRC, expression of NLRC4 (but not NLRP10) and type I IFN genes was associated with a significantly lower risk of metastasis in patients with skin cutaneous melanoma (SKCM)." (PMID 38652550, 2024).
tuberculosis (1 paper, 2017). A chronic, recurrent infection caused by the bacterium Mycobacterium tuberculosis. "We thus sought to determine whether NLRP10 is essential for immunity to Mtb–the etiological agent of tuberculosis." (PMID 29163529, 2017).
vitiligo (1 paper, 2021). Generalized well circumscribed patches of leukoderma that are generally distributed over symmetric body locations and is due to autoimmune destruction of melanocytes. "The upregulated genes in vitiligo lesional skin include markers of inflammation (such as MARCO, NLRP10, PTGS2, and IL36G), oxidative response genes (DUOXA2), and NK cell receptors (NCR3LG1), revealing presence of activated immune response in vitiligo lesions." (PMID 33815367, 2021).
infection (4 papers, 2017 to 2024). The state of being infected such as from the introduction of a foreign agent such as serum, vaccine, antigenic substance or organism. "One study showed that ectopically expressed human NLRP10 colocalizes with NOD1 in HeLa cells upon infection with Shigella flexneri." (PMID 29163529, 2017). "All these cell types are exposed to infection by pathogens, but the different expression profiles of NLRP3, NLRP6, NLRP10, and NLRP12 probably reflects that each cell type has a distinct cell physiology that pathogens would evolve to target." (PMID 39076995, 2024). "Abrogation of NLRP10 expression in epithelial cells reduced IL-8 and IL-6 release due to diminished activation of p38 MAPK, as well as NF-κB–RelA/p65 activity upon HeLa cell infection with S. flexneri." (PMID 29163529, 2017). "Interestingly, T. gondii infection upregulated the expression of NLRC4, NLRP4, NLRP8, NLRP10, NLRP11, NLRP13, and NLRP14 mRNAs at both 4 and 8 h post-infection, but NLRP4, NLRP8, NLRP10, and NLRP11 mRNAs were significantly downregulated at 8 h post-infection compared to that at 4 h post-infection." (PMID 33712075, 2021). "Upon infection with two periodontal pathogens, T. forsythia and F. nucleatum the human oral epithelial cell line HOK-16B reacted with up-regulated mRNA and protein expression of NLRP10 while infection with Streptococcus oralis (S. oralis) did not induce this effect." (PMID 30837987, 2019). "Interestingly, a histologic examination of the lungs from WT and Nlrp10−/− mice 30 days post-infection did not reveal any striking differences in terms of the cellular diversity and composition of the lesions." (PMID 29163529, 2017).
bacterial infections (2 papers, 2013 to 2017). "Our data emphasize the protective nature of NLRP10 against microbial pathogens, thus adding NLRP10 to the group of NLR family members such as NOD1, NOD2, NLRC4, NLRP3, and NLRP12 that initiate pro-inflammatory signaling to mediate host resistance toward bacterial infections." (PMID 29163529, 2017). "While this mechanism is still poorly understood, the ability of NLRP10 to interact with NOD1 as well as its signaling targets RIPK2, TAK1, and NEMO, suggests that NLRP10 may be involved in optimizing cytokine release following bacterial infections." (PMID 24137163, 2013).
cancer (2 papers, 2024 to 2025). A tumor composed of atypical neoplastic, often pleomorphic cells that invade other tissues. "Although the roles of MYRF, CREG2, and NLRP10 in NSCLC have not been extensively studied, their involvement in other cancers has been documented." (PMID 40124684, 2025).
tumor (1 paper, 2020).
NLRP10 also shares sentences with these, for which no sentence is quoted: diabetes (3 papers); allergic contact dermatitis (1); contact dermatitis (1); epilepsy (1); hair diseases (1); inflammatory bowel disease (1); psoriasis (1).